TNF (tumor necrosis factor)
Diseases named in the same sentence as TNF in open-access papers (continued):
Sharing a sentence is not in itself a finding about the gene and the disease.
Obesity (continued). "This was manifested by a reduction in both the expression and the release of proinflammatory cytokines, which are key in the development of obesity-related complications, such as TNF-α, IL-1β, and IL-6." (PMID 31438646, 2019). "In most rodent studies, anakinra (antagonizes both IL-1β and IL-1α), specific anti-IL-1β antibodies, or TNF-α blockers were applied in a preventive fashion in diet-induced mouse obesity models or in the GK rat." (PMID 30989320, 2019). "Tumor necrosis factor-α (TNF-α) reduces insulin receptor substrate tyrosine phosphorylation and is an important mediator of IR in obesity and diabetes." (PMID 31258478, 2019). "Inflammatory cytokines, like TNF and LPS, are elevated in obesity and upregulated adipocyte chemerin." (PMID 30841637, 2019). "Overall, our clinical data confirmed that IL-8 and TNF-α are elevated in individuals with obesity and that these two cytokines are directly and strongly associated with each other and with macrophage markers in human adipose tissue." (PMID 31443599, 2019). "Augmented circulatory interleukins and growth factors such as IL-6 and TNFα respectively have been reported in obesity." (PMID 30669379, 2019). "The parameters for physiological and metabolic changes such as obesity, hypertension, hyperglycaemia, dyslipidaemia, and inflammatory biomarkers (NFκβ p65, TNFα, leptin and adiponectin) were measured." (PMID 31462242, 2019). "For example, TNF-α over expression with obesity signals through IκB kinase β to phosphorylate IRS-1 and IRS-2 to promote insulin resistance, which in turn promotes liver TG accumulation." (PMID 30730895, 2019). "Many previous studies have indicated that IL-6 and TNF-α are involved in obesity-related diseases like atherosclerosis and insulin resistance." (PMID 30854010, 2019). "Plasma IL-8 was found to be increased in individuals with obesity and to be related to adiposity and TNF-α." (PMID 31443599, 2019). "IL-6 and TNF-α are the 2 best-studied cytokines in obesity and have been consistently found to be increased in the serum, white adipose tissue, or both in obese subjects." (PMID 29593725, 2018). "TNF-α has previously been shown to be involved in adipose tissue inflammation and insulin resistance during obesity." (PMID 30319420, 2018). "TNF-α and M30 were significantly associated with US-FLI score in the non-obesity group (both p < 0.05)." (PMID 30671426, 2018). "Obesity promotes a low-intensity inflammatory state, leading to the over-secretion of inflammation mediators such as the tumor necrosis factor (TNF) and interleukin-6 (IL-6), which significantly affect endothelium function and homeostasis." (PMID 30400570, 2018). "In 3T3-L1 adipocytes, increased levels of monosialodihexosylganglioside (GM3) upon TNFα stimulation were found to contribute to insulin resistance in pathological conditions such as obesity." (PMID 29464018, 2018). "Increased adipose tissue mass during obesity increases the circulation levels of TNFα and other adipokines." (PMID 30366378, 2018). "Thus, we hypothesized that obesity-induced TNF-α release may potentiate FM-associated pain." (PMID 29444083, 2018). "Impaired insulin sensitivity is induced by obesity; additionally, higher TNF-α and FFA levels and lower adiponectin levels are identified as major triggers for obesity-induced insulin resistance." (PMID 29718998, 2018). "Inflammation related to obesity can also impair myocyte remodeling as a result of a reduction in protein synthesis due to elevated TNF-α levels." (PMID 29527173, 2018). "Pro-inflammatory macrophages play an important role in adipose tissue inflammation during obesity, as they overexpress genes important in macrophage migration and phagocytosis including TNF, iNOS and IL-6." (PMID 30096208, 2018). "It is unclear if TNF alters monocytosis or specific markers of cellular immunity in the context of obesity." (PMID 30548217, 2018).
Obesity (continued). "Recent studies have confirmed that obesity is a state of chronic inflammation that is characterised by increased concentrations of tumour necrosis factor-alpha (TNF-α), interleukin-6 (IL-6) and other inflammatory markers." (PMID 30914847, 2018). "Third, vanillin reduced elevated levels of inflammatory factors including LPS, IL-6, and TNF-α in plasma and liver tissue resulting from obesity." (PMID 30483238, 2018). "Thesefactors have important roles in cardiovascular dysfunctionsin animals and humans with obesity, diabetes and insulinresistance.Recent in vivo and in vitro findingshave shown that TNF-α induces Apelin gene expression inobese mice." (PMID 29845798, 2018). "Among them, MCP-1, TNFα, interleukin IL-1 and IL-6 have been reported to promote obesity related-insulin resistance." (PMID 29507613, 2018). "TNF-α and IL-6 are pro-inflammatory cytokines synthesized when the lipid content increases in WAT, contributing to the pathogenesis of obesity-linked complications." (PMID 30360535, 2018). "Obesity was identified as a state of chronic, low-grade inflammation due to systemic elevated expression levels of tumor necrosis factor alpha (TNFα) and IL-6." (PMID 30224299, 2018). "Following these early studies showing the importance of TNF-α in mediating metabolic disease in obesity, multiple other cytokines and hormones were also found to play a similar role." (PMID 29868016, 2018). "It is known that the levels of proinflammatory cytokines—a serum tumor necrosis factor (tumor necrosis factor α, TNF-α)—increase in obesity and decrease with weight loss." (PMID 30581847, 2018). "In summary, obesity can elevate the inflammatory cytokine, TNF‐α and CCR2, resulting in increases in albuminuria." (PMID 29632818, 2018). "Obesity is thought to induce a proinflammatory state and adipose tissue releases signals including leptin, TNF-alpha and IL-6." (PMID 30631374, 2018). "Tumor necrosis factor-α (TNF-α) is a key mediator of inflammation that is involved in the development of obesity-related insulin resistance." (PMID 30013128, 2018). "Obesity is also strongly linked to IR, which may be the result of hepatic IR caused by stimulation of the pro-inflammatory M1 macrophages in adipose tissues, which release interleukin-6, tumor necrosis factor-alpha, and free radicals that produce oxidative stress." (PMID 29415050, 2018). "Studies in Chinese, Korean, and South Indian populations have revealed a relationship between polymorphisms in the promoter region of the TNF-α gene and PCOS, hyperandrogenism, type 2 diabetes, and obesity." (PMID 30134857, 2018). "During obesity, immune cells obtain pro-inflammatory characteristics, and recruited macrophages are polarized to secrete pro-inflammatory cytokines including TNF and IL-6." (PMID 30096208, 2018). "In the non-obesity group, hsCRP, triglyceride, ALT, γ-GT, TNF-α, and M30 were significantly associated with US-FLI score using simple linear regression (all p < 0.05)." (PMID 30671426, 2018). "In TNF-α deficient obese mice had lower levels of circulating FFA and were protected from the obesity-related reduction in the insulin receptor signaling in muscle and fat tissues." (PMID 30305178, 2018). "Obesity induces ectopic lipid storage and inflammatory response, accompanied by the secretion of proinflammatory cytokines such as TNFα, IL1β and IL631." (PMID 29961765, 2018). "This was parallel to the normalization in the expression of the macrophage markers F480 and CD68 and of the pro‐inflammatory cytokines TNF‐α and IL‐1β, indicating that FGF21 expression counteracted the inflammation of WAT associated with obesity." (PMID 29987000, 2018). "It was observed that IL-6 and TNF-α inhibit the expression of adiponectin, which is an adipokine, inversely correlated with the obesity, its increase plays an important anti-inflammatory role." (PMID 30201891, 2018).
Obesity (continued). "Obesity is an under-reported predictor of inferior response to anti-TNF agents in patients with select immune-mediated inflammatory diseases." (PMID 29771924, 2018). "In obesity, nutritional stresses promote the secretion of inflammatory cytokines and acute-phase reactants including TNF-α, interleukin (IL)-6, and serum amyloid A in WAT." (PMID 29951059, 2018). "During the progression of obesity or insulin resistance in early metabolic syndrome, tumor necrosis factor-α (TNF-α) is up-regulated while apoA-I production is down-regulated." (PMID 30072955, 2018). "In obesity, the insulin resistant state is always accompanied by the increase of inflammatory cytokines including tumor necrosis factor (TNF)-α, interferon (IFN-γ), interleukin (IL)-1β, interleukin (IL)-6, and monocyte chemoattractant protein (MCP)-1." (PMID 29473848, 2018). "TNF-α can be secreted from both adipose tissue-localized macrophages, which are increased in obesity, and from adipocytes." (PMID 29868016, 2018). "In this systematic review with meta-analysis of 54 cohorts with 19,372 patients with select IMIDs treated with anti-TNF agents, we made several key observations related to the influence of obesity on response to anti-TNF therapy." (PMID 29771924, 2018). "It is known that TNF-α is an inflammatory cytokine synthesised mainly by the white adipose tissue, remarkably in individuals with obesity." (PMID 29322840, 2018). "MCP-1, in concert with other pro-inflammatory cytokines such as TNF-α or IL-6 overexpressed by adipocytes in obesity and MetS, leads to insulin sensitivity." (PMID 29507613, 2018). "Initially, studies showed that adipose tissue expansion in obesity is accompanied by an increase in cytokine and chemokine expression, such as tumor necrosis factor (TNF)-α, interleukin (IL)-6, monocyte chemoattractant protein (MCP)-1, and interferon (IFN)-γ." (PMID 29799467, 2018). "Inflammation in adipose tissue, mediated by cytokines, such as TNF-α, is known to reduce adiponectin levels and contribute to obesity-induced metabolic dysfunction." (PMID 29587377, 2018). "During HFD consumption, excessive fat accumulation in the abdominal fat tissue increases the recruitment of ATMs, producing pro-inflammatory cytokines (e.g. TNFα), which in turn drives obesity-related metabolic disorders." (PMID 29409496, 2018). "Obesity is considered a state of chronic inflammation and secretion of inflammatory biomarkers, including interleuikin-6 (IL-6) and tumor necrosis factor-α (TNF-α)." (PMID 29324697, 2018). "Thus, it is likely that obesity-induced TNF-α release may potentiate FM associated pain." (PMID 29444083, 2018). "In obesity-prone mice, the inhibition of hypothalamic fractalkine reduces obesity-related inflammatory activity as demonstrated by the reduction of TNF-α and IL-1β levels and the decreased recruitment of bone marrow-derived cells to the hypothalamus." (PMID 30618568, 2018). "The cytokine tumor necrosis factor alpha (TNF-α) in adipocytes is positively correlated with the degree of obesity and hyperinsulinemia." (PMID 30597839, 2018). "The antioxidant action of catechins in green tea is likely involved in their anti-obesity mechanism owing to the fact that ROS stimulate NFκB, which in turn promotes the expression of proinflammatory cytokines, such as TNF-α and IL-1β23,24." (PMID 29382887, 2018). "The pathophysiological link between obesity, inflammation, and insulin resistance was first demonstrated when the researchers found the secretion of TNF-α from the adipose tissue of obese rodents." (PMID 29899293, 2018). "Obesity-induced IR was improved by genetic or pharmacological inhibition of inhibitor of κB kinase, which reduces NF-κB pathway activation, thus reducing TNF-α production." (PMID 28661198, 2018). "These inflammations increase the expression of TNF-α and NF-κB, and affect the secretion of metabolic hormones, such as insulin, adiponectin, leptin, and resistin, promoting obesity." (PMID 29707542, 2018).
Obesity (continued). "It has also been seen that adipose tissue TNFα content increased with increasing obesity, however, extremely obese people had relatively low TNFα levels." (PMID 30082376, 2018). "A study have reported that ethanol extract of ginger ameliorated obesity and inflammation through inhibition of adipose tissue accumulation and mRNA expression of pro-inflammatory cytokines such as IL-6 and TNF-α in WAT of mice fed high-fat diet." (PMID 30360535, 2018). "The anthropometric measures, obesity-related biochemical results, and levels of tumor necrosis factor-α, interleukin-6, caspase-cleaved cytokeratin fragment of cytokeratin 18 (M30), and adiponectin were also checked." (PMID 30671426, 2018). "IL-6 and TNF-α are two main proinflammatory cytokines that are significantly increased in obesity patients with excessive WAT." (PMID 30013512, 2018). "Here, we review the current state of knowledge on how obesity affects inflammatory TNFα and IL-6 signaling in hepatocellular carcinoma and colorectal cancers." (PMID 30591653, 2018). "Taken together, these studies demonstrate that TNFα and IL-6, either induced by obesity or the colonic tumor microenvironment, exert their function mainly on infiltrating immune cells and, to a lesser extent, on intestinal cells to promote CRC." (PMID 30591653, 2018). "It is well known that in subjects with obesity, TNF-α expression is high and correlated with hyperinsulinemia." (PMID 30338250, 2018). "Obesity normalizes systemic and skeletal muscle levels of IL‐6 between p50−/− and WT, but elevated TNFα (skeletal muscle and adipose tissue) and IL‐6 (liver and adipose tissue) expression is maintained." (PMID 30251338, 2018). "Studies from the 1990s demonstrated that TNF-α was essential for the development of insulin resistance in high-fat diet-induced obesity in mice and that deletion of TNF-α protected high-fat diet-induced obese mice from developing insulin resistance." (PMID 29868016, 2018). "Inflammation in obesity is characterized by increased blood concentrations of inflammatory markers, including tumor necrosis factor (TNF), C-reactive protein, interleukin (IL) 6, and plasminogen activator inhibitor-1." (PMID 29772784, 2018). "The expression of TNF-α increases in the WAT of obese animals as well as that of human WAT due to obesity, and the expression level of TNF-α in WAT shows a significant positive correlation with body mass index (BMI) and blood insulin concentration." (PMID 28168013, 2017). "On the other hand, while a TNF-α knockout mouse showed the same level of obesity as a control mouse by means of a high fat diet (HFD) feeding, insulin resistance was not shown, and the GLUT4 protein contents in skeletal muscle increased." (PMID 28168013, 2017). "Nevertheless, genetic mouse models provided novel insight into how TNFα-induced signaling interferes with insulin signaling in obesity." (PMID 28233125, 2017). "The SNN extracts significantly improved metabolic disorders including obesity, dyslipidemia, and liver steatosis and reduced hepatic inflammation, circulating tumor necrosis factor-α (TNF-α), and lipopolysaccharide (LPS) levels." (PMID 28831287, 2017). "Adiponectin levels are inadequate in obesity, while leptin (an inflammatory lipokine) augments TNF-α and IL-6 production." (PMID 29064461, 2017). "In obesity, insulin resistance develops as a consequence of metaflammation in which elevated circulating levels of pro-inflammatory cytokines such as TNFα and IL-6 negatively affect the insulin signaling cascade." (PMID 28233125, 2017). "This study evaluated the importance of TNF-α, IL-6, and IL-10 levels and their association with gene polymorphisms in T2DM disease and the obesity." (PMID 28225860, 2017). "Excitingly, we demonstrate in our diet induced obesity mouse model that neutralising ADAM19 therapy results in weight loss, improves insulin sensitivity, and reduces liver TNF-α levels." (PMID 28265178, 2017).
Obesity (continued). "DUSP5 gene expression proportionally increased with increased obesity and this positively correlated to an increase in TNFα." (PMID 29018280, 2017). "Obesity causes chronic inflammation which associates with expression and release of pro-inflammatory cytokines including interleukin-6 and tumor necrosis factor-alpha (TNF-α).16,17 These pro-inflammatory cytokines may cause release of hepcidin from liver or adipose tissue." (PMID 28875005, 2017). "While an increasing number of adipokines are implicated in the development of the obese phenotype, the focus of this review will include MCP-1, IL-6, TNF-α, IL-1β, leptin and adiponectin as the key mediators of AT inflammation and dysfunction in obesity." (PMID 29186929, 2017). "The asthma and obesity groups showed an increase in cytokine of IL-17A, IL-4, IL-6, TNF, IL-1β and IL-18 in the BALF compared with normal controls." (PMID 29160418, 2017). "Recent studies have also reported that PTX inhibited obesity-related steatohepatitis and the subsequent liver tumorigenesis by the suppression of pro-inflammatory cytokines such as TNF-α." (PMID 28212276, 2017). "A strong association has been reported among the extent of infiltrating adipose tissue macrophages, other pro-inflammatory immune cells and several pro-inflammatory mediators (TNF-α, IL-1β, and IL-6), which are enhanced in obesity." (PMID 29064461, 2017). "On the other hand, TNF-α levels were reported to increase in some tissues isolated from obese human populations and rodents showing such rises play a crucial role in obesity-induced inflammation." (PMID 29354072, 2017). "Although the adipose mass considerably increases in obesity, adiponectin concentration is strongly reduced in obese patients due to a chronic inflammation of this tissue, mediated by tumor necrosis factor-α (TNF-α), a suppressor of adiponectin expression." (PMID 29036907, 2017). "MCP-1 recruits macrophages into peripheral sites such as the liver and adipose tissue, which drive the production of TNF-α, described as a potent instigator of obesity-induced insulin resistance." (PMID 29104232, 2017). "A pioneering study from Hotamisligil and Spiegelman identified adipocytes as source of TNFα in the WAT that ultimately impaired insulin signaling in obesity." (PMID 28233125, 2017). "During these obesity-related inflammatory responses, several inflammatory mediators such as tumor necrosis factor-α (TNF-α), monocyte chemoattractant protein-1 (MCP-1), and interleukin-6 (IL-6) are generally involved." (PMID 29081799, 2017). "Obesity is now regarded as an inflammatory condition, which is characterized by increased production and secretion of pro-inflammatory cytokines such as TNFα and IL-6." (PMID 29025435, 2017). "Another major mechanism responsible for CRC is low grade inflammation seen in obesity with increased IL-1b, IL-6, TNF-a and NF-kB." (PMID 28819564, 2017). "There was a significant correlation between hs-CRP, IL-6 and TNF-α with measures of obesity such as BMI and WC." (PMID 29099041, 2017). "Age-related changes in fat tissue inflammatory profiles resemble those in obesity, in which senescent stem cells and endothelial cells accumulate along with an increase in circulating pro-inflammatory cytokines, including TNFα and IL-6." (PMID 28241882, 2017). "Adiponectin, which is inversely affected by obesity and shows a structure similar to TNF-α, has been proposed to antagonize that proinflammatory cytokine by competing with the TNF-α receptor." (PMID 28425943, 2017). "Cytokines, in particular TNFα, IL-1 and IL-6, act as potent stimulators of ROS production by the monocyte-macrophage lineage cells infiltrating adipose tissue in obesity through the activity of NADPH oxidase." (PMID 28582461, 2017).